CDKN2A (cyclin dependent kinase inhibitor 2A)
Diseases named in the same sentence as CDKN2A in open-access papers (continued):
Sharing a sentence is not in itself a finding about the gene and the disease.
tumor (continued). "Consistent with their established tumor suppressor roles in human HCC, PTEN and CDKN2A deficiencies increased porcine HCC cell proliferation and migration." (PMID 39780710, 2025). "The reverse transcription real-time PCR assay revealed higher expression of tumor markers CDKN2A, EGFR, and PDGFRL in monophasic SS." (PMID 41155410, 2025). "A total of 6 expansion cohort patients had both reportable tumor CDKN2A hypomethylation data and qualitative tumor p16 IHC data available." (PMID 41428220, 2025). "CDKN2A also demonstrated significant importance, suggesting their relevance in tumor biology and prognosis." (PMID 40264576, 2025). "For example, the CDKN2A gene (normally upregulated in aging cells to restrain proliferation) is often inactivated by promoter hypermethylation in BC, allowing tumor cells to bypass senescence." (PMID 40918525, 2025). "Promoter hypermethylation, particularly at PRC2 target genes, leads to silencing of key tumor suppressors such as CDKN2A, allowing unchecked cellular proliferation." (PMID 40943058, 2025). "Further features, such as NF1 loss, MAP2K1 mutations, ERBB2 activation, and frequent copy number changes (including CDKN2A/2B deletion and 1p/1q imbalances), add to tumor heterogeneity and evolution." (PMID 41376748, 2025). "Cyclin-dependent kinase inhibitor 2A (CDKN2A), a crucial tumor suppressor gene located at Chr9p21.3, often experiences loss of function due to genomic deletion in this region." (PMID 39983717, 2025). "Among PASE-related genes, cyclin-dependent kinase inhibitor 2A (CDKN2A) showed the most significant upregulation in tumor tissues compared with adjacent normal tissues (|logFC| = 1.38, P< 0.001)." (PMID 41341386, 2025). "Certain mutations were more frequently observed in MGMT IHC negative tumors, particularly those involving genes that regulate the cell cycle, such as DAXX and CDKN2A, which were altered in only primary tumor specimens." (PMID 39825572, 2025). "In the context of CTCL, current research suggests a tumor-suppressive role for METTL3 by modulating CDKN2A expression." (PMID 40332203, 2025). "Two major tumor-suppressor genes, cyclin-dependent kinase inhibitor 2A and 2B (CDKN2A and CDKN2B), as well as a large non-coding RNA ANRIL, are often co-deleted in the core region." (PMID 40046620, 2025). "Most of these specific mutations (n = 20; 80%) were exclusive to NAT, including those affecting key genes such as NOTCH1 (the most mutated gene), FAT1, or PPARD; while 20% were shared between NAT and tumor tissue, affecting genes such as CDKN2A." (PMID 40465458, 2025).
tumor (continued). "Lastly, chromosome 9q cnLOH, including CDKN2A (n = 8/187) and/or NOTCH1 (n = 20/187; mostly mutated for NOTCH1), was identified predominantly in pMMR tumours, and to a lesser extent in dMMR tumours." (PMID 41419736, 2025). "PCR analyses of the first tumor revealed a BRAF V600E mutation, and fluorescence in situ hybridization demonstrated homozygous CDKN2A deletion in both components." (PMID 40231261, 2025). "Among them, the CDKN2A gene is located in the frequently deleted p21 region on chromosome 9 and is widely recognized as a tumor suppressor." (PMID 40256740, 2025). "In the dual-target intervention simulations, upregulating Akt while downregulating CDKN2A resulted in the tumor stable state proportion expanding to 84.73%." (PMID 40244148, 2025). "CDKN2A is a growth suppressor gene that encodes p16(INK4a)/p14(ARF) and is directly associated with tumor immunity, thought to be a prognostic marker in a variety of cancers." (PMID 41184502, 2025). "Two genes related to a favourable immune response, ARG1 and HLA-DQB2, and the tumour markers CDKN2A and KRT7 were selected for validation with qPCR and further analysis." (PMID 39712018, 2024). "If CCNE1 is gained, then the tumor has a greater than 80% chance of being from the pancreas but if it is lost or normal, CDKN2A copy-number status should be assessed." (PMID 39062773, 2024). "In CIN3 versus normal biopsies, the tumour markers CDKN2A and KRT7 had the highest fold-change, while genes related to a favourable immune response, ARG1 and NCAM1, had the lowest." (PMID 39712018, 2024). "Cyclin-dependent kinase inhibitor 2A (CDKN2A, also known as ARF), a well-recognized tumor suppressor, is frequently lost primarily owing to copy number variation (CNV)." (PMID 38273337, 2024). "We observed higher levels of CDKN2A protein in the tumor samples of patients with lower nodal status, N0 vs. N2+N3 (3.8763 (2.8281–8.1203) vs. 2.3377 (1.3179–3.7278); p = 0.0362)." (PMID 39590385, 2024). "CDKN2A is the gene most frequently affected by SCNAs and is deleted in five tumours (14%), a gene in which deletions predict poor outcomes." (PMID 38877653, 2024). "If CDKN2A is gained or normal, the tumor has a slightly greater than 60% chance of being from the pancreas and a 40% chance of being from the small bowel." (PMID 39062773, 2024). "TET2 augmentation contributed to the CDKN2A promoter demethylation, tumor suppressor re-expression, and concomitant resistance to DNMT inhibitors in the DNMT1 gene deleted state." (PMID 39057134, 2024). "The analyses showed that the vast majority of tumor samples had methylation of both CDKN2A/p16INK4A (13/15) and RB1 (11/15)." (PMID 38716944, 2024). "We found that the down-regulated miR-5100 target genes (PLK1, CCNB1, CDKN2A) were significantly upregulated, indicating their tumor-promoting effect in PCa." (PMID 39590378, 2024).
tumor (continued). "The gene CDKN2A, whose gene product is the cyclin-dependent kinase inhibitor 2A, plays an important role in cell cycle regulation and demonstrates tumor suppressor activity." (PMID 38811597, 2024). "In parallel, tumor epithelial cells expressing CDKN2A displayed increased activity in copper metabolism, and this finding was corroborated by correlation analysis in the TCGA cohort." (PMID 38888512, 2024). "In our case, the tumor specimen presented heterozygous deletions of CDKN2A, CDKN2B and CDKN2C, and gains of CDK6 and CCND2." (PMID 38369555, 2024). "Of note, an elevated relative expression level in the PTC HG group was detected only for the CDKN2A (INK4a) gene; it codes for cyclin-dependent kinase inhibitor 2A, which acts as a negative regulator of normal cell proliferation and a tumor suppressor." (PMID 39682560, 2024). "We also found reduced levels of activated NK cells, T cells CD8 and M2 macrophages in tumor tissue from CDKN2A-MUT or DEL pan-cancer patients compared to CDKN2A-WT patients in TCGA cohort." (PMID 38822443, 2024). "In the remaining samples, homozygous deletions in three clinically important tumour suppressor genes, CDKN2A, MAP2K4, and PTEN occurred at analogous percentages in FF and FFPE samples." (PMID 39231944, 2024). "Similar to our study, our research demonstrates that tumor cells expressing CDKN2A exhibit higher glycolytic levels." (PMID 38888512, 2024). "Significantly higher positive rates, OD values, and positive densities of CDKN2A were observed in tumor epithelial cells compared to stromal cells." (PMID 38888512, 2024). "For example, CCND1 and CTTN showed amplification in more than 9 tumor foci, while CDKN2A and CDKN2B exhibited deletion in more than 6 tumor foci." (PMID 38956687, 2024). "The discovered TME landscape can expand our understanding of how CDKN2A mediates resistance to cuproptosis and promotes tumor progression." (PMID 38888512, 2024). "A significantly higher CDKN2A concentration was found in OSCC tumor samples as compared with OPSCC+HPSCC+LSCC." (PMID 39590385, 2024). "Our study reported that CDKN2A protein concentration in the tumor samples in the group of patients with the nodal status N2 or N3 was significantly lower as compared with samples in the group of patients with the nodal status N0." (PMID 39590385, 2024). "Based on our knowledge (PubMed, Medline databases), this has been the first study to analyze the concentrations of CDKN2A and Ki-67 proteins in tumor and surgical margin homogenates obtained from patients with HNSCC by immunoassay (ELISA)." (PMID 39590385, 2024). "Cyclin-dependent kinase inhibitor 2 A (CDKN2A), which encodes the p16INK4a protein, is a well-established tumor suppressor gene." (PMID 39702350, 2024).
tumor (continued). "CDKN2A is known to induce cell cycle arrest through the activation of these downstream effectors, thereby halting cell proliferation and inhibiting tumor growth." (PMID 38438773, 2024). "We examined the transcriptomic heterogeneity in both the tumor regions and the CDKN2A expression rates of each sample." (PMID 38888512, 2024). "We observed a significant difference between OSCC and OPSCC with HPSCC and LSCC tumor groups in CDKN2A level (3.8029 (2.8172–7.9817) vs. 2.9439 (1.8819–3.7261); p = 0.0437)." (PMID 39590385, 2024). "The patient-derived tumor sample Gb14_pr showed the deletion of CDKN2A and CDKN2B and Gb15_pr reported the deletion of 1p." (PMID 38534332, 2024). "CDKN2A codes for the protein, cyclin-dependent kinase inhibitor 2A, which is a potent tumour suppressor protein." (PMID 38164368, 2024). "Differential expression analysis revealed that CDKN2A was highly expressed in tumor epithelial cells compared to normal intestinal epithelial cells, while other cuproptosis-related genes were unchanged." (PMID 38888512, 2024). "Selective clearance of SnCs via pharmacogenetic (CDKN2A‐DTR mice) or pharmacological (ABT263 or D+Q) approaches increased the survival time of tumor‐bearing mice and reshaped the TIME." (PMID 38342629, 2024). "Desirable criteria are MAPK pathway gene alterations and homozygous deletion or mutation of CDKN2A and/or CDKN2B (both present in this tumour), as well as mutation of ATRX and anaplastic histological features (both not present in this tumour)." (PMID 39427038, 2024). "The gene products of CDKN2A act as tumor suppressors, playing a direct role in the regulation of the cell cycle and the negative control of cell proliferation." (PMID 39443269, 2024). "The TAPUR Study, a phase II multi-basket clinical trial, investigated the anti-tumor activity of targeted agents in advanced cancers, including those with CDKN2A genomic alterations." (PMID 38666907, 2024). "Surprisingly, phospho‐CDK4 was also undetectable in two proliferative tumours expressing very low levels of CDKN2A (E7 and L14)." (PMID 36453028, 2024). "In conclusion, the current study demonstrates how low expression of the immune marker ARG1 and high expression of the tumour markers CDKN2A and KRT7 correlate with the group of high oncogenic potential HPV and the development of high-grade CIN." (PMID 39712018, 2024). "The human tumor suppressor CDKN2A has been reported to be more methylated in OS and to be predictive of progression." (PMID 39457378, 2024). "The expression of the CDKN2A gene can result in cell cycle arrest at the G1 phase, leading to the inhibition of cell proliferation and the promotion of tumor cell apoptosis." (PMID 38612764, 2024). "Although CS-like FS had significantly greater SCNAs as well as more chromosomal regions altered that belong to known tumor suppressors, some of these regions were also shared with NS-like FS, including CDKN2A." (PMID 38978078, 2024). "We investigated the CDKN2A gene differential expression between normal and tumor tissues using TIMER2.0." (PMID 38894777, 2024). "In a small number of cases, these genomic bottleneck events resulted in the derivation of PDX models with a different complement of driver alterations from the same tumor (seen in this study affecting CDKN2A, STK11 and MGA)." (PMID 38821942, 2024). "CDKN2A is a known tumour suppressor gene involved in cell cycle regulation, while APC is a critical component of the Wnt signalling pathway." (PMID 38279519, 2024). "In view of this latter finding, a fluorescence in situ hybridization (FISH) test for the CDKN2A gene was ordered, which established its deletion in the tumor." (PMID 39108689, 2024). "In our study, CDKN2A protein levels in the study group were higher in HPV-positive DNA tumor tissue." (PMID 39590385, 2024).
tumor (continued). "Second, our results also demonstrate that CTC analysis brings complementary information to ctDNA in almost 70% of the cases with some CTC ‘private’ mutations in genes implicated in immune evasion or tumor dissemination mechanisms like CTNNB1 and CDKN2A." (PMID 38898234, 2024). "The CDKN2A gene is a tumor suppressor gene that binds and inactivates cyclin-dependent kinase 4 and 6, thus impeding phosphorylation of various growth and regulation factors which control proliferation." (PMID 38607041, 2024). "The identification of marked differences in 5mC methylation for Cdkn2a and Lsamp in the tumor was consistent with reports of their role in cancer." (PMID 39457378, 2024). "The other three sporadic tumor features distanced them further from classic MPNSTs: SP‐01 only has NF1 mutated, and SP‐05 and SP‐06 have only CDKN2A inactivated." (PMID 37798904, 2024). "The results showed the expression of tumor malignant characteristic genes such as CDKN2A CKS1B, HSPA9, IDH2, and MYC among different subpopulations of plasma cells, with high expression in plasma cell_2." (PMID 39271659, 2024). "pUMAP cluster Cdkn2a, a well-known tumor suppressor and senescence gene, is found to impact multiple oncogenes in this analysis, suggesting it as an important player in the network of oncogenic regulation." (PMID 39605490, 2024). "The overexpression of UHRF1 repressed the transcription of such tumor-suppressor genes as CDKN2A, BRCA1, and CDH1 through DNMT1-mediated DNA methylation." (PMID 38725075, 2024). "These tumours have alterations in chromosomal numbers and are associated with mutations in MET, CDKN2A, SETD2, BAP1, PBRM1, NFE2L2, and mTOR genes and have a better prognosis when compared with clear cell RCC in the organ-confined stage." (PMID 38265103, 2024). "The CDKN2A and CDKN2B are tumor-suppressor genes which encodes the Alternate Reading Frame (ARF) protein." (PMID 38593544, 2024). "CDKN2A loss is a key step in pre-MPNST transformation and contributes to drug resistance in other tumor types." (PMID 38480916, 2024). "This tumour also harboured additional genetic abnormalities, including TERT promoter (C228T) mutation, PTEN mutation, and homozygous CDKN2A/2B deletion." (PMID 39014476, 2024). "Compared with that in normal tissue, the expression level of CDKN2A is greater in tumor tissue, which can be a biomarker and reflect the prognosis of cancers." (PMID 39744627, 2024). "CDKN2A and CDKN2B are tumor suppressor genes located at 9p21, and their deletion inevitably increases tumor risk." (PMID 38756785, 2024). "Further inspection of commonly regulated genes revealed that CDKN2A appeared to be the key factor that is up-regulated in the sensitive cell lines, and this has also been reported in other tumor types." (PMID 39500892, 2024). "CDKN2A, also referred to as p16, acts as a tumour suppressor gene that regulates cell cycle progression." (PMID 39120548, 2024). "Conversely, the CDKN2A group showed inhibited sphere-formation of tumor spheres compared to the Vector groups." (PMID 38438773, 2024). "We validated the results in the ScRNAseq cohort and detected the upregulation of MMP7 in CDKN2A-positive tumor cells." (PMID 38888512, 2024). "Further exploration will shed light on the effective targets involved in CDKN2A-regulated cuproptosis and enhance tumor therapy." (PMID 38918694, 2024). "A comparison of 5mC methylation from the nanopore reads of tumor and control samples identified genes with distinct differences including the OS marker Cdkn2a." (PMID 39457378, 2024).